CSE1L (chromosome segregation 1 like)
Diseases named in the same sentence as CSE1L in open-access papers (continued):
Sharing a sentence is not in itself a finding about the gene and the disease.
tumor (continued). "In this study, we investigated the effects of miR-451a and CSE1L on cell viability, proliferation, migration, invasion, and tumor growth in NPC." (PMID 34516344, 2021). "One such predicted target, CSE1L, has been demonstrated to modulate tumor malignancy in various cellular models, and it is highly expressed in NPC cells." (PMID 34516344, 2021). "In the present study, we firstly demonstrated that BANCR and CSE1L expressions were both upregulated in CRC tumor tissues and cells, consistent with earlier studies." (PMID 30144787, 2018). "Results showed that BANCR and CSE1L expressions were both significantly upregulated in CRC tumor tissues (n=32) compared with adjacent normal tissues (n=32)." (PMID 30144787, 2018). "Firstly, RT-qPCR assay was performed to measure expression patterns of BANCR and CSE1L in 32 pairs of CRC tumor tissues and adjacent normal tissues." (PMID 30144787, 2018). "We found that restoration of MSH6 protein expression rescued tumor cell growth and therefore demonstrated that CSE1L effect on cell proliferation was largely dependent on MSH6." (PMID 28387323, 2017). "Both tumor volume and weight were reduced in the CSE1L knockdown group compared to that in the scramble control group." (PMID 28387323, 2017). "The tumor growth curve demonstrated that CSE1L knockdown significantly inhibited tumor growth in vivo." (PMID 28387323, 2017). "All of these alternatively activated growth factor receptors and kinases can reactivate MEK-ERK signaling in vemurafenib-treated (resistance) tumor cells, and will result in CSE1L phosphorylation." (PMID 26070816, 2015). "We used mice tumor xenograft model to study the assay of serum phosphorylated CSE1L for early detecting the efficacy of targeted drugs." (PMID 26070816, 2015). "The phosphorylation status of CSE1L in vemurafenib and sorafenib treated tumor cells were assayed by immunoblotting with antibody against phosphorylated CSE1L." (PMID 26070816, 2015). "We concluded that cytoplasmic CSE1L plays a role in the invasion and metastasis of CRC; furthermore, immunohistochemical analysis of CSE1L distribution in a tumor provides a useful ancillary tool for the prognosis of CRC." (PMID 23369209, 2013). "Even though RAD21 has been previously noted for its copy number amplification helping with tumor immune avoidance and lessening the efficacy of immunotherapy, we also found that CSE1L amplification can facilitate tumor cell invasion through the activation of JAK-STAT and VEGF signaling pathways." (PMID 40406120, 2025). "This suggests that CSE1L may promote OV tumor progression through the activation of the JAK/STAT signaling pathway." (PMID 40406120, 2025). "The results revealed a significantly elevated expression level of CSE1L mRNA in the tumor tissues." (PMID 39430746, 2024). "Moreover, a subcutaneous tumor transplantation test showed that overexpression of CSE1L promoted the proliferation in vivo." (PMID 33854580, 2021). "The results of Co-IP showed the interaction between CSE1L and FLVCR1, indicating that CSE1L might be required for FLVCR1-mediated tumor promotion in ESCC." (PMID 33842377, 2021). "CSE1L affects tumor behavior by changing the function of various genes." (PMID 31383592, 2021). "Besides, CSE1L can be detected not only in tumor tissues but also in body fluids, especially in the blood, indicating that CSE1L can be used as a tumor serum biomarker." (PMID 33842377, 2021). "CSE1L has been reported to be highly expressed in various tumours." (PMID 30485574, 2019). "The high expression of CSE1L in various types of tumours was reported in many studies." (PMID 30485574, 2019). "Additionally, an inverse correlation was observed between miR-203 and BANCR or CSE1L in CRC tumor tissues." (PMID 30144787, 2018). "In this study, we found that BANCR and CSE1L expressions were upregulated in CRC tumor tissues." (PMID 30144787, 2018). "Besides, we found CSE1L expression was correlated with depth of tumor in CRC, consistent with former work." (PMID 30144787, 2018).
tumor (continued). "Moreover, we further demonstrated that BANCR and CSE1L expressions were decreased, while miR-203 expression was increased in tumor tissues derived from sh-BANCR-transfected HCT116 cells." (PMID 30144787, 2018). "The results demonstrated that CSE1L knockdown also dramatically impedes tumor growth in vivo." (PMID 28387323, 2017). "CSE1L is secreted from tumor and its phosphorylation is regulated by ERK1/2." (PMID 26070816, 2015). "In our study, we used an ineffective targeted treatment, i.e. 1 mg/kg lapatinib, as the control treatment, and the results indicated that this treatment neither caused tumor regression nor reduced serum phospho-CSE1L levels in the mice tumor xenograft model." (PMID 26070816, 2015). "Thus, phospho-CSE1L is a potential biomarker for monitoring the emergence of secondary drug resistance after successful initial targeted therapy, at least for detecting tumor resistance to vemurafenib." (PMID 26070816, 2015). "Furthermore, a reduction in CSE1L expression inhibited the metastasis of tumor cells in animal models." (PMID 23369209, 2013). "Thus, stimulation of tumor invasion and metastasis should be the correct role of CSE1L in tumor development." (PMID 23369209, 2013). "We have studied the relationship between CSE1L expression and tumor cell lymphatic vessel invasion and blood vessel invasion, using 60 whole-mount sections of CRC specimens with antibodies against the D2-40 lymphatic endothelial marker and the CD31 blood vessel endothelial marker." (PMID 23369209, 2013). "We studied the effect of CSE1L expression on the invasion and metastasis of tumor cells." (PMID 23369209, 2013). "Depletion of TAZ also attenuates CSE1L-mediated colony formation, motility, and invasiveness in human cancer cells, indicating functional cooperation between CSE1L in TAZ in tumor progression." (PMID 39123485, 2024). "Results showed that PREX1, CSE1L and STAU1 were significantly overexpressed in tumor tissues than in normal tissues in both cohorts." (PMID 37749132, 2023). "To investigate the potential roles of PREX1, CSE1L and STAU1 in CRC pathogenesis, we first compared the expression of these three genes in tumor and adjacent normal tissues in GEO and our own CRC tissues." (PMID 37749132, 2023). "The expression of CSE1L, LOX, RHBDD1, RRBP1 and SOGA1 was significantly higher in tumors than in tumor-adjacent tissue, and the survival analysis of each gene reached the same conclusion." (PMID 36421795, 2022). "Consistent with the results in the TCGA cohort, the mRNA expression of CSE1L, CSTB, MMP10 was significantly up-regulated in HCC while GYS2 was significantly down-regulated when compared with non-tumor tissues." (PMID 31139015, 2019). "Noticeably, the mRNA expression levels of CSE1L and XPOT/6 were highest in tumor pathological grade 4, while the highest mRNA expression levels of XPO1/4/5/7 were found in grade 3." (PMID 31371628, 2019). "That is to say, BANCR knockdown inhibited tumor growth and induced ADR sensitivity in CRC possibly by modulating miR-203/CSE1L axis." (PMID 30144787, 2018). "Immunohistochemistry analysis revealed a marked increase in CSE1L expression in tumor tissues relative to the adjacent non-cancerous tissues." (PMID 39726597, 2024). "Similarly, H&E staining and immunohistochemical analysis (Ki67, PREX1, CSE1L and STAU1) also support the synergistic effect of three genes on tumor growth." (PMID 37749132, 2023). "Interestingly, the group within overexpression of three genes PREX1, CSE1L and STAU1 presented a largest tumor volume among all tested groups." (PMID 37749132, 2023). "In addition, CLDN18 also correlated significantly with markers of activated CD8 + T cells such as MPZL1, CSE1L, CD37, AHSA1, CD3D and IL2RB, after adjusting for tumor purity." (PMID 37438735, 2023). "CSE1L regulates Ras-induced ERK phosphorylation, microvesicle generation, and tumor metastasis." (PMID 36332889, 2022).
tumor (continued). "It is interesting that, the expressions of MYBL2, CSE1L, and most neighbors of NAE1 (59/63) are significantly different between tumor and normal tissues (P-value < 0.05, Wilcoxon rank sum test with continuity correction), but as a link gene NAE1 is not differentially expressed." (PMID 36266635, 2022). "In addition, the expressions of DKC1, NSUN5, FLNA and CSE1L were validated by qRT-PCR and IHC, and found that DKC1, CSE1L and NSUN5 were highly expressed and FLNA was underexpressed in CRC tumor tissues, consistent with the data in TCGA database." (PMID 36319976, 2022). "In this study, it is found that nuclear CSE1L is correlated with cervical lymph node metastasis (p < 0.001), but it was not correlated with grade, tumor size and the extension of neck dissection." (PMID 31383592, 2021). "In addition, our data suggested that the expression levels of ATP11 C, CSE1L, SLC39A14, SLCO5A1, and GLS were higher in tumor tissues than in normal tissue by a factor of 3.4, 4.7, 2.8, 1.7 and 3.6, respectively." (PMID 34516344, 2021). "Moreover, BANCR depletion triggered an elevation of miR-203 expression and a reduction of CSE1L level, suggesting that BANCR downregulation repressed tumor growth and enhanced ADR sensitivity via regulation of miR-203/CSE1L pathway in vivo." (PMID 30144787, 2018). "The results showed that lymphatic or blood vessel invasion was present in sixteen cases (26.6%), but there was no statistic correlation between CSE1L expression and tumor cell lymphatic vessel invasion and blood vessel invasion (data not shown)." (PMID 23369209, 2013). "Several genes located on 20q, for example, the oncogenes located on 20q13.1, such as CAS/CSE1L, NABC1, ZNF217, Aurora2 (BTAK, STK15) and the ubiquitin-conjugating enzyme E2C (UBE2C), have been described to have an important role in tumour progression and liver metastases." (PMID 21673680, 2011). "Similarly, CSE1L demonstrated a negative correlation with the effector genes of these immune cells infiltrating the tumor." (PMID 40406120, 2025). "In addition, CSE1L has been suggested function as a key mediator in cellular proliferation and apoptosis, while PI3K/AKT signaling pathway was documented to closely involve in CSE1L-induced tumor progression." (PMID 37749132, 2023). "Additionally, Spearman’s test found that there existed a negative correlation between miR-203 and BANCR or CSE1L in CRC tumor tissues." (PMID 30144787, 2018). "However, it is not clear whether interaction between miR-451a and CSE1L accounts for the tumor-suppressive effects observed in NPC." (PMID 34516344, 2021).
infection (8 papers, 2010 to 2024). The state of being infected such as from the introduction of a foreign agent such as serum, vaccine, antigenic substance or organism. "Using these screening conditions, more than 80% of siScr-transfected cells were infected, while cells transfected with siRNAs against either CSE1L (siCSE1L) or NXF1 (siNXF1) inhibited infection by more than 85%." (PMID 28272419, 2017).
psychiatric disorder (1 paper, 2021). A disorder characterized by behavioral and/or psychological abnormalities, often accompanied by physical symptoms. "DARS2 is suggested to act as a potential molecular marker of early life stress and vulnerability to psychiatric disorders, and CSE1L plays a role in cellular proliferation and apoptosis." (PMID 34641990, 2021).
CSE1L also shares sentences with these, for which no sentence is quoted: malaria (10 papers); adenocarcinoma (2); parasitemia (2); adenoma (1); brain tumor (1); breast invasive carcinoma (1); Burkitt lymphoma (1); cervical cancer (1); colorectal adenoma (1); cutaneous melanoma (1); diffuse large B-cell lymphoma (1); endometrial adenocarcinoma (1); esophageal squamous cell carcinoma (1); frontotemporal lobar degeneration (1); gastrointestinal disease (1); glioma (1); head and neck cancer (1); Hepatitis (1); iron deficiency (1); larynx cancer (1); liposarcoma (1); liver diseases (1); lung injury (1); nasopharynx cancer (1); non-small cell lung carcinoma (1); Obesity (1); Oral Squamous Cell Carcinoma (1); ovarian tumors (1); preeclampsia (1); rectal cancer (1).
A further 2 diseases each share a sentence with CSE1L in 1 paper.